RC3H1 (ring finger and CCCH-type domains 1)
Description:
Post-transcriptional repressor of mRNAs containing a conserved stem loop motif, called constitutive decay element (CDE), which is often located in the 3'-UTR, as in HMGXB3, ICOS, IER3, NFKBID, NFKBIZ, PPP1R10, TNF, TNFRSF4 and in many more mRNAs. Cleaves translationally inactive mRNAs harboring a stem-loop (SL), often located in their 3'-UTRs, during the early phase of inflammation in a helicase UPF1-independent manner (By similarity). Binds to CDE and promotes mRNA deadenylation and degradation. This process does not involve miRNAs (By similarity). In follicular helper T (Tfh) cells, represses of ICOS and TNFRSF4 expression, thus preventing spontaneous Tfh cell differentiation, germinal center B-cell differentiation in the absence of immunization and autoimmunity (By similarity). In resting or LPS-stimulated macrophages, controls inflammation by suppressing TNF expression (By similarity). Also recognizes CDE in its own mRNA and in that of paralogous RC3H2, possibly leading to feedback loop regulation (By similarity). Recognizes and binds mRNAs containing a hexaloop stem-loop motif, called alternative decay element (ADE) (By similarity). Together with ZC3H12A, destabilizes TNFRSF4/OX40 mRNA by binding to the conserved stem loop structure in its 3'UTR (By similarity). Able to interact with double-stranded RNA (dsRNA). miRNA-binding protein that regulates microRNA homeostasis. Enhances DICER-mediated processing of pre-MIR146a but reduces mature MIR146a levels through an increase of 3' end uridylation. Both inhibits ICOS mRNA expression and they may act together to exert the suppression. Acts as a ubiquitin E3 ligase. Pairs with E2 enzymes UBE2A, UBE2B, UBE2D2, UBE2F, UBE2G1, UBE2G2 and UBE2L3 and produces polyubiquitin chains. Shows the strongest activity when paired with UBE2N:UBE2V1 or UBE2N:UBE2V2 E2 complexes and generate both short and long polyubiquitin chains.
Synonyms: Roquin; KIAA2025; RNF198; RP5-1198E17.5; FHL6; IMDSHY
Tractability: Antibody: the Human Protein Atlas places it where antibodies can reach. PROTAC: its protein half-life has been measured.
Gene: Protein-coding gene on chromosome 1 (173,931,084 to 174,022,357, reverse strand). Ensembl gene ENSG00000135870.
Subcellular location: Cytoplasm, P-body; Cytoplasmic granule
Subcellular location (Human Protein Atlas): Cytosol; Golgi apparatus; Plasma membrane
Gene Ontology:
Molecular function: CCR4-NOT complex binding; double-stranded RNA binding; protein binding; protein-RNA sequence-specific adaptor activity; RNA binding; RNA stem-loop binding; ubiquitin protein ligase activity; ubiquitin-protein transferase activity; miRNA binding; mRNA 3'-UTR binding; mRNA binding; zinc ion binding; metal ion binding
Biological process: nuclear-transcribed mRNA catabolic process; nuclear-transcribed mRNA catabolic process, deadenylation-dependent decay; protein polyubiquitination; regulation of nuclear-transcribed mRNA catabolic process, deadenylation-dependent decay; 3'-UTR-mediated mRNA destabilization; cellular response to interleukin-1; negative regulation of activated T cell proliferation; negative regulation of B cell proliferation; negative regulation of germinal center formation; negative regulation of T-helper 17 cell differentiation; negative regulation of T-helper cell differentiation; nuclear-transcribed mRNA catabolic process, nonsense-mediated decay; P-body assembly; post-transcriptional regulation of gene expression; regulation of germinal center formation; regulation of miRNA metabolic process; regulation of mRNA stability; regulation of T cell receptor signaling pathway; T cell receptor signaling pathway; ubiquitin-dependent protein catabolic process; positive regulation of mRNA catabolic process; protein ubiquitination
Cellular component: cytosol; P-body; plasma membrane; cytoplasmic stress granule; cytoplasm
Genetic constraint (gnomAD): Loss-of-function variants: 46 observed, 127.15 expected, observed/expected ratio (o/e) 0.36, 90% interval 0.28 to 0.46. The upper end of that interval is the gene's LOEUF score, 0.46, which puts it in group 2 of 6, group 1 being the genes least tolerant of losing a copy. Missense variants: 969 observed, 1,370.6 expected, observed/expected ratio (o/e) 0.71, 90% interval 0.67 to 0.75. Synonymous variants: 438 observed, 486.37 expected, observed/expected ratio (o/e) 0.9, 90% interval 0.83 to 0.98.
Homologues: Orthologues: chimpanzee RC3H1 (99% identical), macaque RC3H1 (99% identical), pig RC3H1 (97% identical), dog RC3H1 (96% identical), rabbit RC3H1 (95% identical), mouse Rc3h1 (94% identical), rat Rc3h1 (93% identical), guinea pig RC3H1 (92% identical), tropical clawed frog rc3h1 (80% identical), zebrafish rc3h1b (65% identical), zebrafish rc3h1a (61% identical), Drosophila melanogaster roq (34% identical). Paralogues in human: RC3H2 (51% identical), RNF228 (7% identical), RNF182 (5% identical), RNF227 (3% identical), RNF224 (3% identical).
Diseases named in the same sentence as RC3H1 in open-access papers:
RC3H1 is named in the same sentence as 19 diseases in open-access papers, as found by Europe PMC text mining. Sharing a sentence is not in itself a finding about the gene and the disease. The quoted sentences say what the papers report.
Autoimmunity (6 papers, 2014 to 2019). The occurrence of an immune reaction against the organism's own cells or tissues. "Originally, a missense mutation in the Rc3h1 gene encoding the Roquin-1 protein was identified as the cause of systemic lupus erythematosus-like autoimmunity phenotype in sanroque mice." (PMID 26170170, 2015).
autoimmune disease (4 papers, 2013 to 2024). A disorder resulting from loss of function or tissue destruction of an organ or multiple organs, arising from humoral or cellular immune responses of the individual to their own tissue constituents. "In a Japanese hereditary antithrombin patient with autoimmune disease-like symptoms, a substantial genomic deletion encompassing the RC3H1 gene, encoding Roquin-1, has been documented." (PMID 38491500, 2024). "However, unlike Rc3h1−/− mice which generally lacked autoimmune disease, Roquingt/gt animals that lived to adulthood had a disease phenotype associated with the small intestine and liver that resembled that of Roquinsan/san mice." (PMID 23451046, 2013).
angioimmunoblastic T-cell lymphoma (1 paper, 2022). A mature T-cell non-Hodgkin lymphoma, characterized by systemic disease and a polymorphous infiltrate involving lymph nodes and extranodal sites. "RC3H1 is expressed in BLCA, BRCA, and COAD, and diseases associated with RC3H1 include immune dysregulation and systemic hyperinflammation syndrome and angioimmunoblastic T-cell lymphoma." (PMID 36016607, 2022).
breast carcinoma (1 paper, 2024). "Rc3h1 targets the mRNA of Icos and Ox40 in follicular helper T cells, cell cycle-promoting genes in breast cancer cell lines, and Tfr1 in HAP1, HUVEC, L-M, and MEF cell lines 16,26,27, suggesting Rc3h1 controls the abundance of mRNA in a cell-specific manner." (PMID 39659568, 2024).
lymphoma (1 paper, 2020). A malignant (clonal) proliferation of B- lymphocytes or T- lymphocytes which involves the lymph nodes, bone marrow and/or extranodal sites. "Clinical AITL samples do not show variations in the ring finger and CCCH-type domain 1 (RC3H1/ROQUIN); nonetheless, mice heterozygous for the Roquin missense allele Roquinsan develop AITL-like lymphoma with an approximately 50% penetrance." (PMID 32704161, 2020).
osteoporosis (1 paper, 2024). A condition of reduced bone mass, with decreased cortical thickness and a decrease in the number and size of the trabeculae of cancellous bone (but normal chemical composition), resulting in increased fracture incidence. "Initially, we found upregulated Rc3h1 expression in osteoclasts under the pathologic condition of osteoporosis." (PMID 39659568, 2024).
postmenopausal osteoporosis (1 paper, 2024). Metabolic disorder associated with fractures of the femoral neck, vertebrae, and distal forearm. "The level of Rc3h1 expression was elevated in postmenopausal osteoporosis patients (PMOPs) compared to healthy postmenopausal women." (PMID 39659568, 2024).
infection (2 papers, 2015 to 2018). The state of being infected such as from the introduction of a foreign agent such as serum, vaccine, antigenic substance or organism. "Two of the four modules positively correlated with infection status were enriched for a number of innate and adaptive immune response terms, including both T cell and mast cell processes (e.g. rac1, rc3h1)." (PMID 30285628, 2018).
RC3H1 also shares sentences with these, for which no sentence is quoted: tumor (6 papers); systemic lupus erythematosus (5); Alzheimer disease (1); cancer (1); eosinophilia (1); hemophagocytic lymphohistiocytosis (1); immune deficiencies (1); Lymphadenopathy (1); schizophrenia (1); Splenomegaly (1); T-Cell Lymphoma (1).